AFP (alpha fetoprotein)
Diseases named in the same sentence as AFP in open-access papers (continued):
Sharing a sentence is not in itself a finding about the gene and the disease.
tumor (continued). "In addition to tumor markers (AFP and CAE), a decrease in the serum level of the liver and kidneys, LPO and NO, TNF-α level, as well as the expression level of Bcl-2 was observed in the RJ-treated group compared to the control EST group." (PMID 38892209, 2024). "In addition to traditional biomarkers, AFP, newer blood-based biomarkers such as ctDNA, microRNAs, circulating tumor cells, and exosomes are being investigated for their utility in HCC diagnosis and prognosis." (PMID 39650722, 2024). "Our research results indicate that the MVI-positive group and MVI-negative group have statistically significant differences in tumor diameter, AFP level, presence of hypoechoic halo around the tumor, irregularity of nodule margins, tumor enhancement pattern, and early washout time." (PMID 39759152, 2024). "Furthermore, the inhibitory effects of CSS in combination with sorafenib on serum tumour markers (AFP and CA19‐9) and liver function markers (ALT and TBIL) were stronger than those of sorafenib alone." (PMID 38613352, 2024). "However, the results of this study should be interpreted cautiously because of the limited number of patients included in this study, and the fact that tumor size and the timing of AFP measurement varied between patients." (PMID 38792380, 2024). "The propensity-score model included gender, serum alpha-fetoprotein (AFP) levels before treatment (≤ or > 400 ng/ml), tumor numbers (single or multiple), liver involvement (unilateral or bilateral), macrovascular invasion (absent or present), and distant metastasis (absent or present)." (PMID 39507533, 2024). "As proof-of-concept demonstrations,this strategy is employed to design peptides for a variety of targetproteins, ranging from a tumor marker (alpha fetoprotein, AFP) totwo virus surface proteins (SARS-CoV-2 RBD and norovirus P-domain),with ultrahigh affinities in the nanomolar range." (PMID 39634215, 2024). "Timely diagnosis, supported by imaging studies such as ultrasound and measurement of serum tumor markers, such as alpha-fetoprotein (AFP), beta-human chorionic gonadotropin (HCG), and lactate dehydrogenase (LDH), are critical in determining tumor type and staging." (PMID 39697937, 2024). "In terms of AFP origin, the histological features seen in the tumor resection specimen, with AFP-positive mucinous intestinal epithelium, may well explain the high serum AFP observed here." (PMID 38098239, 2024). "In our MGCT data, almost all abnormal AFP values were 5 times higher than the upper limit of the institution’s normal value, and a value 5 times higher than the upper limit of the normal is usually an indicator of tumor recurrence." (PMID 38001671, 2023). "Previously, high serum AFP concentrations were moderately correlated with tumor size." (PMID 36890813, 2023). "Tumor size, AFP level, and type of surgery also had a significant effect on DSS." (PMID 36883222, 2023). "Notably, several studies have found that commonly used tumor biomarkers, such as carcinoembryonic antigen, alpha fetoprotein, glycoantigen 125, glycoantigen 199, and glycoantigen 72-4, exhibit lower sensitivity than ctDNA." (PMID 37351260, 2023). "Tracing the effect of CCL4, tumor markers AFP and GGT were analyzed in sera of animals." (PMID 37835585, 2023). "AFP has been a well‐established tumor biomarker of HCC for decades." (PMID 38130028, 2023). "While CA 12-5 was slightly elevated, the tumor markers AFP, HCG and CA 15-3 were in a normal range." (PMID 36873804, 2023). "The tumor marker alpha-fetoprotein (AFP) was within normal ranges." (PMID 38107062, 2023). "Moreover, METTL1 overexpression in HCC correlated with low expression of the tumor suppressor PTEN, increased tumor size, tumor vascular invasion, higher serum Alpha-Fetoprotein (AFP) level, and poor prognosis." (PMID 37612540, 2023). "Additionally, several clinical variables were different between the 2 clusters in the TCGA datasets, including AFP value, pathological stage, T stage, and tumor weight." (PMID 36765548, 2023).
tumor (continued). "The Milan and University of California San Francisco (UCSF) transplantation selection criteria are based on morphological variables (tumor size and number), but there is increasing evidence that the biological marker alpha-fetoprotein (AFP) is a powerful predictor of tumor recurrence." (PMID 36900345, 2023). "Additional tumor markers have been tested, including alpha‐fetoprotein (AFP), carcinoma embryonic antigen, carbohydrate antigen (CA)‐153, CA199, CA125, CA724, serum ferritin, squamous cell carcinoma antigen, and neuron‐specific enolase all of which were within normal limits." (PMID 37772674, 2023). "By performing a detailed analysis of tumor stage, low serum AFP, liver disease etiologies, and pre-HCC diagnosis samples, we aim to provide an in-depth understanding of the applicability of these markers in patients with highly diverse HCC characteristics in these regions." (PMID 37708457, 2023). "The significant differences between these groups were age (52.09 ± 13.43 versus 49.15 ± 11.99, p = 0.002), NEU (59.08 ± 18.66 versus 63.30 ± 13.62, p = 0.001), serum AFP (p < 0.001), tumor numbers (p < 0.001) and tumor diameters (5.39 ± 3.14 versus 7.01 ± 3.01, p < 0.001)." (PMID 37118720, 2023). "Immune cell profiling at this time point using multiplex flow cytometry revealed a significant upregulation of CD8+ T cells and a downregulation of B cells in the liver tissues from the anti–PD-L1 combination group compared with the AFP immunized group and tumor control group." (PMID 37040183, 2023). "Serum AFP level can be used to monitor tumor recurrence or metastasis." (PMID 37161409, 2023). "Furthermore, there was substantially more area of ROC from APF + IL-34 in predicting the incidence of HCC, compared to that from AFP alone, despite similar observed patterns between IL-34 + AFP vs tumor size, and AFP vs tumor size." (PMID 35347503, 2023). "This included liver function tests and tumor markers (AFP, CEA, and CA 19-9)." (PMID 37430153, 2023). "HCC is routinely diagnosed, prognosed, and screened using the tumor biomarker AFP." (PMID 37189672, 2023). "On the other hand, a remarkable decrease in survival and increase in the recurrence rate are associated with tumors which are beyond Milan criteria, number, size of the tumor, high levels of AFP (> 400 ng), the presence of vascular invasion and the poorly differentiated tumors." (PMID 36564609, 2023). "The tumor growth-promoting and immunosuppressive activities of AFP may hamper the efficacy of immunotherapy." (PMID 37958306, 2023). "Furthermore, the expression of GLS1 is correlated with serum AFP level, tumour differentiation, lymphatic metastasis, and TNM stage in patients with HCC." (PMID 37946141, 2023). "This study showed that AFP response to LRT was a predictor for tumor recurrence in HCC after LDLT." (PMID 36900345, 2023). "Tumor and patient characteristics may impact the tumor response to these locoregional therapies, including alpha-fetoprotein (AFP) levels, performance status, neutrophil-to-lymphocyte ratio, and Child–Pugh classification." (PMID 37686496, 2023). "The dynamic change in AFP was indicative of the tumor’s biological behavior, which was complicated." (PMID 36900345, 2023). "In giant mixed GCTs, small foci of YST, the source of AFP, may be accidentally overlooked during the examination of tumor samples." (PMID 37686577, 2023). "A model was established by integrating AFP, tumor number, AST/ALT ratio, and BCLC." (PMID 36944920, 2023). "In addition to that, the pooled hazard ratio of the included studies showed that Milan criteria, level of AFP, presence of vascular invasion, tumor differentiation were significant predictors of recurrence." (PMID 36564609, 2023). "The AFP model exhibited better predictive performance in post-LT tumor recurrence than the Milan criteria in hepatitis C virus-related HCC patients and has been applied to select HCC candidates for LT by the Liver Transplantation French Study Group for organ sharing." (PMID 37988413, 2023).
tumor (continued). "Alpha-fetoprotein (AFP) is the main tumor marker used for HCC surveillance." (PMID 37568778, 2023). "Therefore, it can add valuable information to other preoperative findings, such as tumor size, tumor number and AFP value." (PMID 35451699, 2023). "AFP immunization synergizes with anti–PD-L1 to inhibit cMet/β-catenin tumor progression." (PMID 37040183, 2023). "However, only a small number of factors are considered for the BCLC stage, and some other factors related to the prognosis of HCC patients, including AFP level, longest tumor diameter, presence of cirrhosis, and platelet count, are ignored." (PMID 36675418, 2023). "A randomized phase III trial suggested that tumor marker AFP and β-HCG response following one cycle of bleomycin, etoposide, and platinum (BEP) in men with poor-risk disease may have important prognostic value." (PMID 37138865, 2023). "Moreover, univariate Cox analysis identified AFP level (p = 0.012), number of tumor (p < 0.001), MVI (p < 0.001), TNM stage (p < 0.001) and RNF2 expression (p = 0.002) to be risk factors for HCC patients." (PMID 37037816, 2023). "Moreover, high PD-L1 expression on inflammatory cells of the tumor microenvironment correlated with poor prognostic features, such as high AFP levels, macrovascular invasion, poor differentiation, and high PD-1 expression." (PMID 37189643, 2023). "Tumor markers like AFP, CA199, CA125, and CEA were in normal range in all patients." (PMID 37046258, 2023). "However, when we analyzed the baseline characteristics between the two therapy groups, there were significant differences in terms of BCLC stage, Child–Pugh class, serum AFP level, tumor size, portal vein invasion, distant metastasis, and previous treatment." (PMID 37686509, 2023). "Furthermore, a meta-analysis of eight datasets, with different subgroups based on clinical parameters such as tumor size and Alpha-fetoprotein (AFP) levels, showed that subclass S2 was characterized by AKT activation in combination with MYC." (PMID 38003445, 2023). "Serum AFP levels may reflect tumor burden, and a decrease in the serum AFP level after surgery is considered to indicate a good response to treatment." (PMID 37124520, 2023). "After 10 cycles of camrelizumab and continuous oral administration of lenvatinib, the tumor exhibited striking shrinkage in volume indicating a partial radiological response, accompanied by a reduction in the alpha-fetoprotein levels, followed by salvage resection." (PMID 36721173, 2023). "Multivariable Cox regression analyses showed that pretreatment oncological features, including ≥4 tumors, tumor size >10 cm, and tumor rupture, as well as clinical factors, such as decompensated liver function and AFP ≥400 ng/mL, were statistically significant predictors of poorer OS." (PMID 37346065, 2023). "In addition to tumor size, AFP is a surrogate marker for tumor microvascular invasion; such invasion is also a known predictor of poor outcomes." (PMID 36900125, 2023). "Notably, it has also been reported that AFP levels are an essential indicator of tumor size, which has a negligible impact on overall survival." (PMID 36638133, 2023). "The only analysed factors with significant impact on tumor recurrence and mortality in our group of patients were the total AFP at the time of transplant and the relation of the highest measured AFP value before treatment and the AFP value after chemotherapy at the time of liver transplantation." (PMID 36832331, 2023). "Furthermore, the AFP vaccine effectively prevented c-MYC/Mcl1 HCC initiation when administered before tumor formation, while it was ineffective against full-blown c-MYC/Mcl1 tumors." (PMID 37040183, 2023). "Similarly, age, tumor number, postoperative AFP, postoperative protein induced by vitamin K absence or antagonist-II (PIVKA-II), and ECOG PS were incorporated for the prediction of RFS." (PMID 37689775, 2023).
tumor (continued). "Monitoring PIVKA-II levels in HCC transplant recipients reflects the tumor early recurrence after transplantation and could be used, complementing AFP and imaging tests, as a novel biomarker of this pathology." (PMID 37024609, 2023). "AFP internalization by cancer cells through the AFPR is associated with enhanced growth and malignant behaviour of tumors, consistent with the observation of modestly increased tumor growth in unconjugated ACT-101 group in this study." (PMID 37016369, 2023). "To analyse the relationship between L1 expression in HCC and other clinical characteristics of the patients in the TCGA cohort, we parsed the dataset with clinical characteristics including age, gender, ancestry, aetiology, pathological grade, patient AFP levels and tumour invasion." (PMID 36707636, 2023). "Furthermore, clinicopathological analysis showed that only AFP and tumor number were significantly associated with PD-1 expression, whereas PDL-1 expression was significantly correlated with age and tumor size." (PMID 37047482, 2023). "Researchers have developed other serum tumor markers for clinical use, including AFP-L3%, lectin-bound AFP, and PIVKA-II (protein induced by vitamin K absence or antagonists-II); however, those markers are unable to detect small HCC tumors in roughly 30% of patients." (PMID 37760434, 2023). "This case, however, did not have the lowest AFP levels; rather, a high-risk tumor was presented with the lowest AFP values." (PMID 38201440, 2023). "Increasing tumor stage, portal vein tumor thrombus (PVTT), hepatitis B surface antigen (HBsAg), hepatitis B virus-DNA (HBV-DNA) copy number and elevated alpha-fetoprotein (AFP) level have been reported to be associated with early recurrence." (PMID 37007138, 2023). "As a standard control, a significant correlation between AFP and tumor size was observed." (PMID 35347503, 2023). "In the training cohort, 11 variables were significantly associated with worse OS at univariable Cox regression analysis, and four of them (i.e., incomplete tumor “capsule”, mosaic architecture, tumor multiplicity, and serum AFP > 400 ng/mL) were included in the final model at multivariable analysis." (PMID 37191923, 2023). "Additionally, the incidence of liver metastasis was higher (37.4% vs. 62.6%) and tumor size was smaller in the high-AFP group." (PMID 37161409, 2023). "Multivariate analysis revealed that albumin (HR: 1.451, p < 0.001), creatinine (HR: 1.270, p = 0.003), AFP > 200 ng/mL (HR: 1.709, p < 0.001), vascular invasion (HR: 1.673, p < 0.001) and tumor size > 5 cm (HR: 1.855, p < 0.001) were independent predictors associated with shortened survival." (PMID 37046586, 2023). "Although consensus on the optimal criteria for LT patient selection in HCC is yet to be reached, the likely direction is that the tumor burden limit will be expanded and that a composite criterion will be implemented, where markers beyond tumor size, such as AFP, will be considered." (PMID 38001637, 2023). "In other words, a low AFP level and small tumor diameter may reflect less tumor biological aggressiveness, which results in better clinical outcomes after LT." (PMID 36967432, 2023). "Logistic regression analysis showed that KIAA1522 was significantly correlated with the T stage (P=0.003), histologic grade (P < 0.001), AFP (P < 0.001), tumor status (P=0.022),and had a trend of correlation with pathologic stage (P=0.088) and vascular invasion (P=0.082)." (PMID 36761433, 2023). "The authors performed a sub-group analysis to determine the prognostic factors in lenvatinib-treated patients, taking into account the age (≥ or <75 years), the AFP level (≥ or <400 ng/mL), the tumor diameter (≥ or <50 mm), the number of liver tumors (≥ or <10), and the C-P score (5 or 6)." (PMID 38201479, 2023). "Moreover, significant univariate associations with OS were shown for macrovascular invasion, ECOG PS 2, maximum tumor diameter > 10 cm, AFP > 400 ng/mL, and PIVKA‐II ≥2000 mAU/mL." (PMID 36790032, 2023).
tumor (continued). "The ratio of AFP-L3 to AFP increases with the malignancy of the tumour." (PMID 37957550, 2023). "For the C model’s features, four features were selected: PVTT, tumor number, AFP, and GGT." (PMID 37700255, 2023). "In univariate analysis, our data demonstrated that high AFP (≥400 ng/mL), large tumor size (≥ 5 cm), BCLC stage C, low serum miR-122 level (<4.1 log10 copies) and high serum miR-221 level (≥4.0 log10 copies) were predictive factors for overall TACE refractoriness in patients with HCC." (PMID 37685331, 2023). "The AFP ratio was a reliable biomarker for tumor recurrence." (PMID 37124520, 2023). "Tumor marker detection showed serum alpha-fetoprotein (AFP) level (1.86ng/ml), carbohydrate antigen 125 (CA125) level (11.30U/ml), carbohydrate antigen 19 − 9 (CA19-9) level (10.9U/ml), and carcinoembryonic antigen (CEA) level (3.23ng/ml), which were no obvious abnormalities." (PMID 37518334, 2023). "Furthermore, univariate analysis showed that AFP (P = 0.015), tumor numbers (P < 0.001), maximum tumor diameter (P = 0.01), and BCLC stage (p < 0.001) were statistically correlated with OS." (PMID 36944920, 2023). "Notably, although the tumor size and stages were comparable between polyploid and near-diploid HCCs, the serum alpha-fetoprotein (AFP) level was significantly higher in polyploid HCCs." (PMID 37715023, 2023). "In addition, elevated serum AFP levels were observed to be positively correlated with the poor differentiation, microvascular invasion and tumor recurrence, which is consistent with the biological behavior of GPC3-positive HCCs." (PMID 38023195, 2023). "Furthermore, we identified several factors affecting OS, such as patient age, serum AFP level, tumor differentiation (i.e. grade), and T stage using the SEER database." (PMID 37106014, 2023). "AFP is a marker of increased disease progression to neoplasia." (PMID 37686577, 2023). "This study showed that risk factors, or “annotation factors,” that influenced the EFS included pretreatment extent of disease (PRETEXT), older age, elevated alpha‐fetoprotein (AFP), vascular involvement, multifocal disease, extrahepatic extension, tumor rupture, and metastasis." (PMID 37962078, 2023). "Of them, alpha-fetoprotein (AFP) serves as a tumor biomarker for clinical diagnosis of HCC." (PMID 36769597, 2023). "AFP immunization synergizes with anti–PD-L1 to dramatically inhibit c-MYC/Mcl1 tumor progression." (PMID 37040183, 2023). "We identified independent risk factors using a Cox regression analysis, including age, sex, AFP level, the grading and staging of the tumor, the size of the tumor, and whether the patient was receiving therapy like surgery and chemotherapy." (PMID 38001570, 2023). "This study was intended to explore the expressions of circSLCO1B7 in the tissues and plasma of HCC patients and analyze the relationship between the expression of circSLCO1B7 and the clinical data of patients, such as age, sex, HBV infection, TNM stage, lymph node metastasis, tumor size and AFP." (PMID 38015711, 2023). "The median values of tumor markers, such as AFP and PIVKA-II, tended to increase." (PMID 36980626, 2023). "Furthermore, we examined the association between MRPL48 expression and clinical characteristics of patients with HCC and determined that MRPL48 expression was correlated with T classification, pathological tumor grade, AFP level, and vascular invasion." (PMID 38093387, 2023). "Furthermore, CHK1 expression was significantly correlated with patients with higher BMI (>25), advanced tumor stage (T stage), and higher AFP level (>400 ng/mL)." (PMID 36765808, 2023). "Furthermore, we identified some potential prognostic biomarkers for HCC, a highly malignant tumor with high incidence and mortality rates, including AFP, H2AC19, KLF11, and IFNG." (PMID 37107646, 2023). "Additionally, tumor recurrence in patients with AFP >100 ng/ml was significantly higher than those with AFP ≤100 ng/ml11." (PMID 37988413, 2023).